TRPV1 (transient receptor potential cation channel subfamily V member 1)
Description:
Non-selective calcium permeant cation channel involved in detection of noxious chemical and thermal stimuli. Seems to mediate proton influx and may be involved in intracellular acidosis in nociceptive neurons. Involved in mediation of inflammatory pain and hyperalgesia. Sensitized by a phosphatidylinositol second messenger system activated by receptor tyrosine kinases, which involves PKC isozymes and PCL. Activated by vanilloids, like capsaicin, and temperatures higher than 42 degrees Celsius. Upon activation, exhibits a time- and Ca(2+)-dependent outward rectification, followed by a long-lasting refractory state. Mild extracellular acidic pH (6.5) potentiates channel activation by noxious heat and vanilloids, whereas acidic conditions (pH <6) directly activate the channel. Can be activated by endogenous compounds, including 12-hydroperoxytetraenoic acid and bradykinin. Acts as ionotropic endocannabinoid receptor with central neuromodulatory effects. Triggers a form of long-term depression (TRPV1-LTD) mediated by the endocannabinoid anandamine in the hippocampus and nucleus accumbens by affecting AMPA receptors endocytosis.
Synonyms: VR1
Tractability: Small molecule: an approved drug acts on it; a structure with a bound ligand is known; a high-quality ligand is known; it belongs to a druggable protein family. Antibody: UniProt places it where antibodies can reach, with high confidence; its Gene Ontology location is reachable by antibodies, with high confidence; UniProt predicts a signal peptide or a membrane-spanning region. PROTAC: a small molecule that binds it is known. Other modalities: a drug acting on it is in phase 2 or 3 trials.
Target class: Voltage-gated ion channel; Ion channel; Transient receptor potential channel
Chemical probes: AM404, CAPSAICIN, MAVATREP
Safety:
Unwanted effects reported when the protein is acted on. In parentheses: how it was acted on, where the effect was seen, and who reports it.
neurotoxicity (source: ClinPGx)
Gene: Protein-coding gene on chromosome 17 (3,565,444 to 3,609,411, reverse strand). Ensembl gene ENSG00000196689.
Subcellular location: Postsynaptic cell membrane; Cell projection, dendritic spine membrane; Cell membrane
Pathways (Reactome):
Transport of small molecules: TRP channels
Gene Ontology:
Molecular function: extracellular ligand-gated monoatomic ion channel activity; phosphoprotein binding; protein binding; ATP binding; calcium channel activity; calmodulin binding; excitatory extracellular ligand-gated monoatomic ion channel activity; intracellularly gated calcium channel activity; phosphatidylinositol binding; transmembrane signaling receptor activity; voltage-gated calcium channel activity; monoatomic ion channel activity; temperature-gated ion channel activity
Biological process: calcium ion import across plasma membrane; cellular response to acidic pH; cellular response to heat; response to capsazepine; thermoception; calcium ion transmembrane transport; cell surface receptor signaling pathway; cellular response to alkaloid; cellular response to ATP; chemosensory behavior; protein homotetramerization; calcium ion import into cytosol; calcium-mediated signaling; detection of temperature stimulus involved in sensory perception of pain; excitatory postsynaptic potential; monoatomic ion transmembrane transport; monoatomic ion transport; negative regulation of transcription by RNA polymerase II; transmembrane transport
Cellular component: membrane; plasma membrane; postsynaptic membrane; dendritic spine membrane; GABA-ergic synapse; neuron projection
Genetic constraint (gnomAD): Loss-of-function variants: 83 observed, 79.28 expected, observed/expected ratio (o/e) 1.05, 90% interval 0.88 to 1.26. The upper end of that interval is the gene's LOEUF score, 1.26, which puts it in group 5 of 6, group 1 being the genes least tolerant of losing a copy. Missense variants: 1,061 observed, 1,064.6 expected, observed/expected ratio (o/e) 1, 90% interval 0.95 to 1.05. Synonymous variants: 514 observed, 452.65 expected, observed/expected ratio (o/e) 1.14, 90% interval 1.06 to 1.22.
Homologues: Orthologues: chimpanzee TRPV1 (99% identical), macaque TRPV1 (97% identical), dog TRPV1 (89% identical), rabbit TRPV1 (88% identical), guinea pig TRPV1 (87% identical), mouse Trpv1 (87% identical), pig TRPV1 (86% identical), rat Trpv1 (86% identical), tropical clawed frog trpv1 (60% identical), Caenorhabditis elegans osm-9 (20% identical), Caenorhabditis elegans ocr-4 (20% identical), Drosophila melanogaster nan (20% identical), and 1 more. Paralogues in human: TRPV4 (44% identical), TRPV2 (41% identical), TRPV3 (37% identical), TRPV6 (25% identical), TRPV5 (25% identical).
Diseases named in the same sentence as TRPV1 in open-access papers:
TRPV1 is named in the same sentence as 483 diseases in open-access papers, as found by Europe PMC text mining. Sharing a sentence is not in itself a finding about the gene and the disease. The quoted sentences say what the papers report.
Obesity (105 papers, 2011 to 2026). Accumulation of substantial excess body fat. "Previous studies have elucidated the involvement of TRPV1 in regulating transcription factors associated with adipogenesis and combating obesity." (PMID 39104411, 2024). "For example, TRPV1 activation prevented HFD-induced obesity in mice, an effect that was associated with increased expression and deacetylation of PPAR-γ in the epididymal fat of these mice." (PMID 36589466, 2022). "This implies that altered TRPV1 activity can be associated with a compensatory response that counteracts the hypertension in this model of obesity." (PMID 33716794, 2021). "Experiments on high-fat diet mouse indicate the impairment of TRPV1 response to mechanic stretch as the cause of overeating and obesity." (PMID 31263706, 2019). "TRPV1 has also been implicated in insulin resistance and obesity, characteristic of type 2 diabetes." (PMID 24861977, 2014). "Previous studies on TRPV1-targeted therapy have focused mostly on relieving discomfort, such as pain and itching caused by the disease, and with increasing research, TRPV1 has been recognized as a potential target with preventive effects against obesity." (PMID 40677717, 2025). "This study provides in vivo evidence for the critical role of BAT mitochondrial Ca2+ homeostasis in obesity-associated hypertension and indicates that the TRPV1/UCP1/LETM1 complex may be an alternative intervention target." (PMID 35043013, 2022). "Interestingly, the intake of low doses of dietary capsaicin, a TRPV1 activator, has been associated with improved clinical signs in obesity and T2D." (PMID 35455971, 2022). "Interestingly, TRPV1 knockout mice exhibit a younger metabolism as well as a longer lifespan, predicting that TRPV1 is associated with metabolic disorders, obesity, and aging." (PMID 36277193, 2022). "Abundant evidence supports the hypothesis that altered TRPV1 expression and/or function is associated with vascular dysfunction in diabetes and obesity." (PMID 33716794, 2021). "The polymorphism of TRPV1, rs4790522, with the AA genotype was associated with a higher salt recognition threshold (lower salt taste sensitivity) in people with hypertension and obesity." (PMID 34150338, 2021). "In addition, the polymorphism TRPV1, rs4790522 with AA genotype was associated with a higher salt recognition threshold (lower salt taste sensitivity) in people with hypertension and obesity." (PMID 34150338, 2021). "Cumulatively, the studies reviewed above, support the hypothesis that TRPV1 channels protect from aging-associated obesity." (PMID 21483038, 2011). "Moreover, obesity in the old Trpv1 KO mice was associated with insulin resistance." (PMID 31344877, 2019). "Therefore, given its plausible involvement in regulation of energy and glucose homeostasis and its dysregulation in obesity, TRPV1 may be a target for weight loss therapy and diabetes." (PMID 30108548, 2018). "The clinically safe TRPV1 antagonist XEN-D0501 is currently under development as an oral drug for overactive bladder; undoubtedly, these findings provide valuable clinical data for the development of TRPV1-targeted drugs to treat obesity." (PMID 40677717, 2025). "When TRPV1 is activated, it regulates downstream pathways and participates in the regulation of obesity." (PMID 40677717, 2025). "Increasing evidence suggests that TRPV1 plays a key role in the regulation of body weight and lipid metabolism and is therefore considered a potential target for the treatment of obesity." (PMID 40677717, 2025). "In this paper, we present novel separable cryo-microneedles patches delivered with capsaicin integrated mesoporous dopamine (mPDA) for obesity treatment through activating TRPV1 and inducing lipid droplet dissolution." (PMID 40903781, 2025). "Although a large body of evidence points to a relationship between the development of obesity and TRPV1, the relationship between the two is still controversial in some studies." (PMID 40677717, 2025).
Obesity (continued). "Although CAP’s anti-obesity and lipid-lowering effects via TRPV1 activation have been demonstrated, its therapeutic potential against MASLD and associated insulin resistance remains poorly defined." (PMID 40864772, 2025). "In this work, by combining the recent mechanism of the role of TRPV1 in neuroendocrine regulation, we hope to provide novel approaches to block or even reverse the development of obesity." (PMID 40677717, 2025). "Our research presents novel findings that TRPV1 activation by CAP at thermoneutrality counters obesity in WT mice and promotes PRDM-16-dependent UCP-1 transcription." (PMID 39204203, 2024). "The systemic response resulting from the activation of TRPV1 (among other TRPs) plays a role in adipocyte thermogenesis, adipogenesis, adipose tissue inflammation, and obesity, as well as water retention." (PMID 38927688, 2024). "Our research presents novel findings that demonstrate that TRPV1 activation by CAP at thermoneutrality counters obesity in WT mice and promotes PRDM-16-dependent UCP-1 transcription." (PMID 39204203, 2024). "Our data indicate for the first time that TRPV1 activation counters obesity at thermoneutrality permissive for UCP-1 and the enhancement of PRDM-16 is not beneficial in the absence of UCP-1." (PMID 39204203, 2024). "Previous studies have also shown that capsaicin activated TRPV1 to improve endurance capacity and energy metabolism, counter obesity, and intervene diabetes." (PMID 38913071, 2024). "Our data indicate for the first time that TRPV1 activation counters obesity at thermoneutrality permissive for UCP-1 and that the enhanced expression of other thermogenic genes and proteins is not beneficial in the absence of UCP-1." (PMID 39204203, 2024). "Decreased TRPV1 expression in mice has been found to protect against diet-induced obesity and promotes oxygen consumption, fat oxidation, and locomotor activity." (PMID 38927688, 2024). "This work systematically analyzed the role of TRPV1 activation in countering obesity in WT mice housed in the TNZ and delineated the mechanism of UCP1 activation in energy expenditure in the TNZ using WT and UCP-1−/− mice." (PMID 39204203, 2024). "We found that the intragastric administration of capsaicin significantly blunted increases in body weight, food intake, blood lipid, and blood glucose in TRPV1−/− mice fed a high-fat diet, suggesting an anti-obesity effect of capsaicin." (PMID 39201665, 2024). "TRPV1 channels play a major role in various disorders, such as pain, depression, stress, obesity and anxiety, and are known to be involved in various acupuncture effects." (PMID 37384285, 2023). "Novel therapeutic approaches including intra-articular administration of inhibitors of key pain mediators such as NGF and TRPV-1 have yielded promising early results but are yet to be studied in the context of obesity." (PMID 38275369, 2023). "The role of the TRPV1 receptor in the process of WAT browning after treatment with capsaicin aiming to prevent diet-induced obesity in wild-type and TRPV1 (−/−) mouse models were evaluated." (PMID 37564131, 2023). "In animal models, dietary CAP triggered the browning of white adipose tissue in mice, counteracting obesity through the activation of TRPV1 channel-dependent mechanisms." (PMID 37998493, 2023). "Capsaicin markedly upregulated genes involved in glucose metabolism and modulated gut microbiota by activating the TRPV1, indicating the anti-obesity of capsaicin." (PMID 38084147, 2023). "Transient receptor potential cation channel subfamily V member 1 (TRPV1) is part of the mammalian somatosensory system, and capsaicin-induced activation of TRPV1 has shown beneficial effects in diabetes, obesity, and liver injury." (PMID 37528882, 2023). "Our previous studies demonstrated that knockout of TRPV1 exacerbated an obesity-induced renal injury and nocturnal hypertension in mice." (PMID 37047183, 2023).
Obesity (continued). "In humans, a reduced TRPV1 expression in visceral adipose tissue from obese individuals was reported, which was accompanied by reduced CAP-induced calcium influx, highlighting the potential to activate TRPV1 channels to prevent obesity." (PMID 37998493, 2023). "In mice, TRPV1 channels attenuate diet induced obesity and insulin resistance, and TRPV1 activation counters diet induced obesity through BAT activation." (PMID 36017333, 2022). "Dietary capsaicin activated its receptor, transient receptor potential vanilloid 1 (TRPV1), and converted adipose tissues from white to brown, which contributed to reducing obesity." (PMID 36615777, 2022). "To further determine the importance of ROS production in the promotional effect of TRPV1 knockout on obesity-related hypertension induced by UCP1 knockout, we added tempol, an ROS scavenger, to the feed of TRPV1/UCP1 double knockout mice." (PMID 35043013, 2022). "Noteworthy, TRPV1 plays a substantial role in the obesity pathogenesis, with important consequences for hepatic health." (PMID 35455971, 2022). "Leptin resistance and altered energy balance have been attributed to obesity in TRPV1-null mice fed HFD." (PMID 35455971, 2022). "In summary, the knockout of TRPV1 and UCP1 in mice at the same time induced severe obesity and obesity-associated hypertension." (PMID 35043013, 2022). "To determine how TRPV1 deficiency affects obesity induced by UCP1 knockout, we generated TRPV1/UCP1 double knockout mice (TRPV1−/−/UCP1−/−) by crossbreeding TRPV1−/− mice with UCP1−/− mice." (PMID 35043013, 2022). "Deletion of TRPV1 also protected from obesity-induced hypertension, low-grade inflammation, and glucose tolerance." (PMID 36589466, 2022). "Although the mechanism of action of Capsaicin involves multiple tissues, its anti-obesity effects are mediated by the activation of the sympathetic nervous system via TRPV1 on sensory neurons." (PMID 35459786, 2022). "The TRPV1 channel has become a potentially relevant target for metabolic intervention, including insulin resistance, obesity, type 2 diabetes, and nonalcoholic fatty liver, due to its presence in a variety of metabolic tissues." (PMID 35806020, 2022). "In obesity studies, activation of TRPV1 is detrimental because high fat leads to enhanced TRPV1 expression." (PMID 36424928, 2022). "We found that the regulatory effect of TRPV1 on LETM1 was critical to restrain obesity and related hypertension, and the knockout of TRPV1 further exacerbated obesity in UCP1 knockout mice, resulting in more severe hypertension." (PMID 35043013, 2022). "This study showed that the activation of TRPV1 channels by capsaicin helped in adipogenesis and obesity prevention." (PMID 35164163, 2022). "In this study, we show that the promotional effect of TRPV1 deficiency on BAT whitening and obesity induced by UCP1 knockout relies on aggravated mitochondrial Ca2+ disorder and ROS production." (PMID 35043013, 2022). "Capsaicin induces WATB and fights obesity by activating the TRPV1 (transient receptor potential cation channel, subfamily V, member 1) channel-dependent mechanism in obesity treatment." (PMID 35886989, 2022). "Chili pepper consumption has been suggested to provide various health benefits, including cancer-preventive, anti-inflammatory, and anti-obesity effects via TRPV1-dependent and TRPV1-independent mechanisms." (PMID 34371974, 2021). "During states of pancreatic inflammation, TRPV1 activation increases expression of calcitonin gene-related peptide, known to disrupt insulin release from pancreatic β-cells, promoting IR and obesity." (PMID 34673019, 2021). "This questions the effectiveness of capsaicin treatment to prevent obesity in males because of dysfunction of the capsaicin-TRPV1 dependent mechanism in the adipose tissue." (PMID 35011580, 2021). "Obesity-related inflammation promotes PKC stimulation in the vascular wall that phosphorylates TRPV1 and sensitizes the channel to capsaicin, heat, and acid action." (PMID 35011580, 2021).